ZNF583 (zinc finger protein 583)
Description:
May be involved in transcriptional regulation.
Synonyms: FLJ31030
Tractability: PROTAC: ubiquitination databases record sites on it.
Gene: Protein-coding gene on chromosome 19 (56,397,966 to 56,436,035, forward strand). Ensembl gene ENSG00000198440.
Subcellular location: Nucleus
Subcellular location (Human Protein Atlas): Nucleoli; Cytosol
Pathways (Reactome):
Gene expression (Transcription): Generic Transcription Pathway
Gene Ontology:
Molecular function: DNA-binding transcription factor activity, RNA polymerase II-specific; RNA polymerase II cis-regulatory region sequence-specific DNA binding
Biological process: regulation of transcription by RNA polymerase II; regulation of DNA-templated transcription
Cellular component: nucleus
Genetic constraint (gnomAD): Loss-of-function variants: 28 observed, 55.04 expected, observed/expected ratio (o/e) 0.51, 90% interval 0.38 to 0.7. The upper end of that interval is the gene's LOEUF score, 0.7, which puts it in group 2 of 6, group 1 being the genes least tolerant of losing a copy. Missense variants: 469 observed, 671.72 expected, observed/expected ratio (o/e) 0.7, 90% interval 0.65 to 0.75. Synonymous variants: 199 observed, 220.53 expected, observed/expected ratio (o/e) 0.9, 90% interval 0.8 to 1.01.
Homologues: Orthologues: chimpanzee ZNF583 (99% identical), macaque ZNF583 (98% identical), pig ZNF583 (91% identical), rabbit ZNF583 (90% identical), guinea pig ZNF583 (88% identical), mouse Zfp583 (83% identical), rat Zfp583 (82% identical). Paralogues in human: ZNF570 (65% identical), ZNF480 (44% identical), ZNF551 (40% identical), ZNF256 (39% identical), ZNF79 (39% identical), ZNF304 (39% identical), ZNF792 (39% identical), ZSCAN2 (37% identical), ZSCAN20 (37% identical), ZNF548 (36% identical), ZNF418 (36% identical), ZNF549 (36% identical), and 26 more.
Diseases named in the same sentence as ZNF583 in open-access papers:
ZNF583 is named in the same sentence as 10 diseases in open-access papers, as found by Europe PMC text mining. Sharing a sentence is not in itself a finding about the gene and the disease. The quoted sentences say what the papers report.
osteosarcoma (2 papers, 2023 to 2024). A usually aggressive malignant bone-forming mesenchymal neoplasm, predominantly affecting adolescents and young adults. "In our study, we observed notable variations in ZNF583 protein expression during experimental validation between osteosarcoma and human osteoblast cell lines." (PMID 37980450, 2023). "The results revealed elevated levels of CGNL1 and CXCL13 in osteosarcoma cell lines, while ZNF583 was markedly downregulated." (PMID 37980450, 2023). "Our qRT-PCR analysis demonstrated that osteosarcoma cells expressed higher levels of CGNL1 and CXCL13 compared to osteoblast cells, while ZNF583 had the opposite effect, indicating its potential as a novel anti-oncogene." (PMID 37980450, 2023). "Signature (ZNF583, CGNL1, CXCL13) was developed to predict overall survival in osteosarcoma patients, targeting the anoikis subcluster." (PMID 37980450, 2023). "Furthermore, ZNF583's role in tumor microenvironment (TME), microsatellite instability (MSI), immune cell infiltration, and immune checkpoint regulation was also observed in pan-cancer settings, in addition to its involvement in osteosarcoma progression." (PMID 37980450, 2023).
cervical cancer (1 paper, 2023). A primary or metastatic malignant neoplasm involving the cervix. "Our findings indicate that ZNF583 amplification was the primary type of alteration present in cervical cancer patients, while mutational copy number alteration (CNA) and copy number deep deletion were predominant in colorectal cancer and head and neck cancer, respectively." (PMID 37980450, 2023).
cancer (2 papers, 2022 to 2023). A tumor composed of atypical neoplastic, often pleomorphic cells that invade other tissues. "Accordingly, we utilized the cBioportal database to investigate the mutant landscape of ZNF583 in diverse types of cancer." (PMID 37980450, 2023). "When compared with normal paracancerous tissues, several cancer types exhibited significant variations in ZNF583 expression." (PMID 37980450, 2023). "A thorough investigation was carried out to explore ZNF583 expression in various cancer types, aiming to comprehend its involvement in cancer." (PMID 37980450, 2023). "ZNF583 was predominantly found to be downregulated in most of the examined cancers." (PMID 37980450, 2023). "Furthermore, few publications have examined the correlation between ZNF583 and cancer." (PMID 37980450, 2023).
neoplasia (2 papers, 2018 to 2023). "Our result reveals that ZNF583 is positively linked with activated NK cells, potentially influencing their recruitment or activation within the tumor microenvironment." (PMID 37980450, 2023).
ZNF583 also shares sentences with these, for which no sentence is quoted: Chronic colitis (1 paper); colorectal cancer (1); dysplasia (1); glioblastoma (1); head and neck cancer (1); Intellectual disability (1).